NANOG (Nanog homeobox)
Diseases named in the same sentence as NANOG in open-access papers (continued):
Sharing a sentence is not in itself a finding about the gene and the disease.
tumor (continued). "For example, thyroid mesenchymal carcinoma cells carrying the stem cell markers NANOG and Oct4 were able to initiate tumor growth after transplantation into immunodeficient mice." (PMID 39776907, 2024). "Gain or amplification of the NANOG locus is common in advanced tumours, suggesting a key role for this master regulator of pluripotency in TGCT stemness and malignancy." (PMID 38693576, 2024). "Through gain-of-function experiments, MIR9-2 was further investigated as a novel tumour suppressor regulated by NANOG." (PMID 38693576, 2024). "The qRT-PCR analysis results of tumor tissue lysates showed that the overexpression of TSP50 promoted the mRNA expression of BCSC-related markers NANOG, OCT4 and ALDH1." (PMID 39030572, 2024). "This signature, comprising TRP53BP1, P21, BAX, CYCLIN D1, OCT-4, and NANOG, appears to influence tumor response to radiation." (PMID 39594660, 2024). "These cells rely on expression of stem cell transcription factor genes including SOX2, MYC, and NANOG to generate tumor spheres in vitro and tumors in vivo with high frequency." (PMID 38886396, 2024). "231DD shows enhanced expression of ES-TFs SOX2, MYC, and NANOG and tumor sphere formation compared to vector control 231 cells." (PMID 38886396, 2024). "In this study, we showed that the expression of MIR9-2 is lower in EC and SEM than in normal testes and that its expression is lower in tumours expressing high levels of NANOG." (PMID 38693576, 2024). "We observed an expression of CD24, CD44, and NANOG, indicating a highly potent capacity to rebuild the tumor mass." (PMID 39408826, 2024). "Due to its properties, NANOG is also a therapeutic target; inhibiting its signaling pathways has been shown to reduce tumor proliferation and provide a more efficient therapeutic response." (PMID 39459448, 2024). "On the other hand, class II HDACs, particularly HDAC7, are associated negatively with pluripotency markers’ expression in most tumor types, except for OCT4 (encoded by POU5F1), and NANOG in KIRC, KIRP, LGG, LUAD, LUSC, PRAD, and THCA." (PMID 39063083, 2024). "After the interaction of Abelson interaction factor 2 (ABI2) and TF MEOX2, MEOX4 and NANOG promoter regions bind to activate transcription, promoting the phenotype of CSCs and inducing tumor recurrence in HCC." (PMID 38561775, 2024). "The analysis of miRNA expression in tumour samples stratified according to NANOG expression demonstrated that most miRNAs were differentially expressed between NANOG H/L (401 miRNAs), followed by NANOG M/L (321 miRNAs) and by NANOG H/M (97 miRNAs)." (PMID 38693576, 2024). "And the expressions of tumor proliferation markers Ki67 and tumor stemness markers (NANOG, CD133, OCT4, and SOX2) all obviously reduced compared with the controls." (PMID 39692209, 2024). "NANOG can also stimulate autophagy, a process by which tumor cells can degrade and recycle certain components under stress conditions (in the case of therapy)." (PMID 39459448, 2024). "SMG exposure increased the expression of the NANOG gene in adherent and floating cells, driving the transformation in tumor cells." (PMID 39451527, 2024). "To investigate TRPV1 as a target for impeding NANOG-driven autophagy in cisplatin-resistant tumor cells, we monitored TRPV1 expression in cisplatin-susceptible or -resistant tumor cells." (PMID 37165076, 2023). "Based on preliminary data, YAP1 interaction with β-CATENIN and NANOG seems to play an important role, as removing β-CATENIN from the HBx and HBx + NANOG models decreased colony formation and tumor incidence." (PMID 37744383, 2023). "The co-expression of constitutively active β-CATENIN with NANOG promotes self-renewal ability and tumor-initiating ability of hepatoblasts." (PMID 37744383, 2023). "In contrast, NANOG expression significantly associated with higher TNM stage, higher tumor grade, and higher Ki-67 LI." (PMID 37627900, 2023).
tumor (continued). "NANOG, a cell‐fate regulatory molecule known to be important for embryonic stem cell self‐renewal, also plays an important role in tumor development." (PMID 37667739, 2023). "Western blot analysis of tumor tissues validated that the protein expression of NANOG and SOX2 was significantly lower in the IL20RB knockdown group than in the control group." (PMID 38098005, 2023). "NANOG was found expressed in the tumour parenchyma of the tissue samples of AME with cytoplasmic and nuclear marking, as well as in the AME-hTERT lineage, in this study." (PMID 36655039, 2023). "IHC of tumor tissue sections showed that the protein levels of NANOG and SOX2 in the IL20RB knockdown group was significantly lower than those in the control group." (PMID 38098005, 2023). "Taken together, our findings indicate that the TRPV1 channel plays an important role in the secretory autophagy-dependent refractory phenotypes of NANOG+ tumor cells." (PMID 37165076, 2023). "Dysregulation in the expression genes of the pluripotency gene networks including OCT4, SOX2, NANOG and REX1 have been implicated in tumor development, and have been observed to result in poorer patient outcomes." (PMID 36980876, 2023). "The upregulation of NANOG and BMI1 expression was associated with increased MycN expression, as well as the elevated spheroid growth and tumor-initiating capacity of NB cells, in mice." (PMID 36980635, 2023). "Consistently, the increased expression of NANOG was also observed in another cisplatin-resistant tumor model (SiHa CR)." (PMID 37165076, 2023). "To verify the potential role of EGF in the NANOG-mediated cisplatin resistance in tumor cells, we neutralized EGF with a specific monoclonal antibody in CaSki NANOG cells." (PMID 37165076, 2023). "Compared to the miR-135b-5p-low group, higher expression of CD24, C-MYC, and NANOG was observed in the miR-135b-5p-high group within stem-like or malignant cell clusters, suggesting more remarkable stemness properties of tumor cells in this group." (PMID 36755690, 2023). "Taken together, we propose that NANOG+ tumor cells enriched by selective pressure imposed by cisplatin treatment preferentially expressed TRPV1 via transcriptional regulation." (PMID 37165076, 2023). "Direct blocking of NANOG through siRNA resulted in tumor growth inhibition and increased cell lysis through CTLs." (PMID 38071322, 2023). "Knockdown of TAZ or NANOG significantly increased apoptosis in tumor cells and suppressed the growth of tumor introduced by mechanical inputs." (PMID 36646707, 2023). "For instance, hypoxia stimulates HIF-1α- and HIF-2α-dependent expression of ALKBH5, which demethylates NANOG mRNA and increased the percentage of breast CSCs in the tumor microenvironment." (PMID 37015927, 2023). "Previously, we defined a NANOG signature to acquire a more reliable readout indicating NANOG expression in tumor cells." (PMID 35104240, 2022). "In most cases, undifferentiated tumor cells express associated embryonic markers such as the OCT4, NANOG, SOX2, and CARM1 genes." (PMID 35274101, 2022). "As well as STAT3, it has been shown that suppression of STAT1 reduces the formation of lung A549 tumor spheres which was maintained by the suppression of factors associated with stemness, such as SOX2, OCT4, and NANOG." (PMID 35205716, 2022). "Consistent with the results, we showed that a NANOGhigh tumor with CTL-refractory property exhibited resistance to trastuzumab-mediated CDC, whereas silencing of NANOG led to increase in susceptibility of trastuzumab-mediated CDC." (PMID 35606403, 2022). "Mouse hepatocytes that express HCV-NS5A in liver upregulate the expression of Toll-like receptor 4 (TLR4) and develop liver tumors containing NANOG positive, tumor-initiating stem-like cells (TICs)." (PMID 36187761, 2022).
tumor (continued). "CHFR was considered a key element for NANOG mediated multi-resistance and stem-like phenotype in immune-edited tumor cells." (PMID 35813831, 2022). "Resistance of tumor cells to T cell–mediated killing by the NANOG/HDAC1 axis is essential for inducing the immune-refractory feature in the TME." (PMID 35104240, 2022). "Previously, we demonstrated that NANOG is a key TF driving multi-modal resistance in immune-edited P3 tumor cells." (PMID 35606403, 2022). "Our choice of SC markers was based on our report in the BM18 xenograft model of PC that cells surviving castration and able to reinitiate tumor growth are characterized by the coexpression of ALDH1A1 or NANOG together with the luminal marker NKX3-1." (PMID 36185585, 2022). "The effect of toyocamycin on p21, ID2, OCT4, SOX2 and NANOG expression was also verified in the tumor sections by immunohistochemistry." (PMID 35078502, 2022). "In doing so, we discovered that the TF NANOG plays a crucial role in cross-resistance to CDC during CTL-mediated immunoediting of tumor cells." (PMID 35606403, 2022). "IHC analysis showed that overexpression of RICH1 significantly inhibited the expression of YAP/TAZ and CSCs-associated markers (ALDH1A1, NANOG, OCT4, and SOX2) in transplanted tumor tissues." (PMID 35064101, 2022). "Although we observed significant suppression of tumor growth in NANOG-Cxcl10 WT tumor–bearing mice compared with mice in the other groups, these tumors continued to grow." (PMID 35104240, 2022). "Due to the direct interaction between SOX2/NANOG/BMI1/KLF4 in the invasiveness of tumor cells, as well as its biological significance in the progression of ESCC, SOX2 expression can enhance malignancy by inducing stemness properties and EMT in ESCC." (PMID 36553636, 2022). "NANOG is a known inducer of a stem cell-like state that has been found aberrantly expressed in many kinds of tumours." (PMID 36291854, 2022). "For instance, NANOG was a major transcription factor that enhances secretory autophagy in tumor cells via promoting LC3B expression, leading to EGF autocrine." (PMID 36300110, 2022). "Conversely, CXCR4 overexpression strikingly counteracted the effect of PTX on decreasing Akt phosphorylation and reductions in N-cadherin, vimentin, snail, CD44, CD133, and NANOG protein expression in SKOV3 tumor tissues (*P<0.05)." (PMID 35681259, 2022). "C1GalT1-mediated truncation of O-glycans on CD44 inactivates the ERK/NF-κB signaling pathway, resulting in NANOG expression in pancreatic cancer (PC) cells and changes in tumor stem cell characteristics." (PMID 35936713, 2022). "NANOG expression in tumor cells determines the response to anti–PD-1 therapy by altering the immune feature of the TME." (PMID 35104240, 2022). "We have previously reported that high level of NANOG was correlated with tumor progression and poor outcome of patients with cervical cancer." (PMID 35606403, 2022). "Mice implanted with MDA-MB-231 NTC or A2BR knockdown subclones were treated with 10 mg/kg paclitaxel every 5 days for three doses and tumor samples were collected for ChIP followed by qPCR with primers flanking FOXO3 binding site of NANOG, SOX2 and KLF4 genes." (PMID 35401817, 2022). "Critically, NANOG+ tumor cells enriched through selective pressure imposed by CTLs preferentially expressed CD59 via transcriptional regulation, thereby promoting the CDC-refractory phenotype." (PMID 35606403, 2022). "Elimination of HSP90 activity in tumor cells inhibited their migration, invasiveness and metastatic potential, while activation of the NANOG-dependent HSP90/TCLA1/AKT signaling pathway augmented significantly the stemness of tumor cells." (PMID 36612107, 2022). "Signaling by EPHA10 and its ligand, EFNA4, promotes OSCC cell migration and tumor spheroid formation through induction of NANOG mRNA expression via ERK activation." (PMID 33436772, 2021).
tumor (continued). "Our in vitro and in vivo studies indicated that SOX2, relative to OCT4 and NANOG, correlates with 3-D spheroid growth, tumor-initiating capacity, and chemoresistance." (PMID 33445692, 2021). "Dual IF staining of stemness-associated markers with RAS components was performed to investigate if these components were expressed by the NANOG+ CA CSC-like subpopulation on the tumor epithelium and by an OCT4+ cell subpopulation in the stroma of CA tissues." (PMID 34428252, 2021). "For example, exogenous IL33 stimulation or IL33 overexpression in tumor cells confers stemness on tumor cells through ST2 signaling to activate NANOG, NOTCH, and OCT3/4 in colon cancer and hepatocellular carcinoma." (PMID 33535613, 2021). "Eight of the 12 cases stained positively for NANOG and this was consistently seen in the cytoplasm of tumor cells." (PMID 34685477, 2021). "An analysis of patient data suggested a stronger role for SOX2, relative to OCT4 or NANOG, for tumor relapse potential." (PMID 33445692, 2021). "NANOG not only contributes to the regulation of pluripotency in stratified epithelia; it also mediates tumor cell proliferation, epithelial-mesenchymal transition and escape from immune system." (PMID 34201050, 2021). "Several studies reported the correlation between NANOG expression and tumor metastasis, revealing itself as a powerful biomarker of poor prognosis." (PMID 34638956, 2021). "In prostate cancer, NANOG overexpression leads to enhanced clonal growth, tumor regenerative capacity, and resistance to castration." (PMID 33420371, 2021). "Stem-cell transcription factor NANOG activates fatty-acid oxidation in HCC-tumor-initiating cells to support self-renewal and drug resistance." (PMID 33747521, 2021). "SOX2, relative to OCT4 or NANOG, is a stronger indictor of chemoresistance, tumor-initiation, and recurrent disease." (PMID 33445692, 2021). "NANOG in HCC tumor-initiating cells suppresses oxidative phosphorylation to support self-renewal and drug resistance." (PMID 33747521, 2021). "The mouse anti-NANOG primary antibody (green) produced a weaker stain than the rabbit anti-NANOG (red), but was detected in the cytoplasm of tumor epithelial cells, which showed cytoplasmic and membranous expression of AT2R (red)." (PMID 34428252, 2021). "In this regard, we have identified the transcription factor (TF) NANOG as a key intrinsic factor that renders immune-edited tumor cells impervious to cytotoxicity of T cells." (PMID 31992715, 2020). "NANOG, a pluripotency factor, was necessarily required for primary tumor formation and distant metastasis, because of its povital role in the maintenance and specification of cancer stem cells." (PMID 32742194, 2020). "NANOG mRNA was present in all tumor samples tested; however, it was undetectable in 10 TANT samples." (PMID 32733958, 2020). "We also observed a strong cytokeratin 18 staining, and a mild decrease of NANOG signal on IHC staining of ATO/ CDDP combined treated tumor sections." (PMID 32351887, 2020). "IRX4 knockdown in a PC-9/GR xenograft tumor model inhibited tumor progression and the expression of NANOG and CD133 more effectively than single treatment alone." (PMID 32820157, 2020). "Noteworthy, CD163+ TAM infiltration was inversely and significantly correlated with NANOG expression, in both the stroma (p = 0.001) and tumor nests (p = 0.03)." (PMID 32630659, 2020). "We found a strong positive correlation between NANOG and mRNA levels of all the tested protein regulators in tumor tissue samples, indicating that these regulators affect NANOG expression in OSCC, too." (PMID 32733958, 2020). "NANOG is involved in the self-renewal of embryonic stem cells; a previous study indicated that NANOG gene is abnormally overexpressed during the development of malignant phenotype of tumor cells." (PMID 32812032, 2020).
tumor (continued). "Along with the finding that the centrosomal localization of NANOG was observed among various tumor and non-tumor cell types, these results provide the first evidence suggesting a common centrosome-specific role of NANOG." (PMID 32168958, 2020). "Such CD133+ TICs have also been isolated from three other HCC animal models and patient HCC tissues and were characterized by their NANOG-dependent self-renewal and tumor-initiating activities." (PMID 32555153, 2020). "Our study also uncovered striking differences in the prognostic impact of NANOG expression, depending on the tumor site and lymph node infiltration." (PMID 32635524, 2020). "In line with this, knockdown of JMJD2B led to a decrease in NANOG expression in the xenograft tumor tissues." (PMID 32684087, 2020). "Then, we calculated the correlation between the methylation ratio of NANOG promoter and expression of NANOG in tumor samples using the Spearman rank-order correlation." (PMID 32733958, 2020). "One population within the tumor niche had the markers SOX2+/NANOG+/KLF4+/c-MYC+/OCT4−, and two populations in the peritumoral stroma had the markers SOX2+/NANOG+/KLF4+/c-MYC+/OCT4− and SOX2+/NANOG+/KLF4+/c-MYC+/OCT4+." (PMID 32974184, 2020). "In this study, we demonstrated the crucial role of HSP90A at the crossroads between NANOG signaling and the multi-aggressive properties of immune-edited tumor cells by identifying HSP90AA1 as a NANOG transcriptional target." (PMID 31992715, 2020). "NANOG is a transcription factor that is a key regulator of pluripotency in stratified epithelia, and mediates tumor cell proliferation, epithelial–mesenchymal transition, and escape from immune system." (PMID 32630659, 2020). "In the process, NANOG mediates the pro-survival and stem-like phenotype of the immune-edited tumor cells through the AKT pathway." (PMID 31992715, 2020). "Here, we report that HSP90A is a clinically actionable target for NANOG-mediated multi-aggressive properties of immune-edited tumor cells." (PMID 31992715, 2020). "It was described that the AD-01 treatments suppressed both the self-renewal capacity of breast CSCs in vitro and tumor initiation in vivo, while the stemness markers NANOG, OCT4, and COX2 were reduced in the treated cells." (PMID 32268506, 2020). "Our findings implicate that the HSP90A-TCL1A-AKT pathway ignited by NANOG is a central molecular axis and a potential target for immune-refractory tumor." (PMID 31992715, 2020). "Further, combined use of gefitinib and IRX4 knockdown significantly downregulated NANOG protein level in vitro, and markedly decreased tumor growth and the expression of NANOG and CD133 in vivo, than treatment with gefitinib alone." (PMID 32820157, 2020). "On the contrary, the non-CSC population (i.e., CD34− cells), which constitutes the bulk of the tumor, confirmed a high D2 and NANOG expression level at the early stages of tumorigenesis, one and two weeks following tumor induction." (PMID 32197405, 2020). "Data available for NANOG expression in head and neck SCC are mostly based on immunohistochemistry or immunofluorescence, and they suggest that NANOG expression is upregulated in SCC and associated with tumor development, transformation, and metastasis." (PMID 32733958, 2020). "Recent studies have shown that the NANOG gene is an important tumor stem cell marker involved in cell proliferation, renewal, and pluripotency." (PMID 33336042, 2020). "QYHJ, especially GEM + QYHJ treatment, was significantly increased the mRNA expression of lncRNA AB209630, significantly decreased the mRNA levels of miR373, EphB2 and NANOG, and markedly reduced the tumor sphere formation and the numbers of CD133+ stem cells." (PMID 31147453, 2019). "Reduction of nestin expression impairs sphere formation, in vivo tumor growth, and the expression of stem cell markers such as NANOG, N-cadherin, CD133, and Oct4." (PMID 31752169, 2019).